SMAD5 (SMAD family member 5)
Diseases named in the same sentence as SMAD5 in open-access papers (continued):
Sharing a sentence is not in itself a finding about the gene and the disease.
Insulin resistance (1 paper, 2023). Increased resistance towards insulin, that is, diminished effectiveness of insulin in reducing blood glucose levels. "MiR-155 was implicated in osteogenesis inhibition through the regulation of SMAD5, and SOCS1 expression was detected in exosomes derived from obese adipose tissue and promoted insulin resistance." (PMID 36831188, 2023).
iron deficiency (1 paper, 2020). "SMAD5 also controls levels of the master iron regulator hepcidin, which may be elevated and drive iron deficiency associated with poor outcomes in PAH." (PMID 32352834, 2020).
ischemia (1 paper, 2021). A hypoperfusion of the BLOOD through an organ or tissue caused by a PATHOLOGIC CONSTRICTION or obstruction of its BLOOD VESSELS, or an absence of BLOOD CIRCULATION. "Smad5 mRNA levels also increased following ischemia with a peak at day 5 (9.2-fold compared to control muscle) and then rapidly decreased to lower levels (threefold the control value at day 14)." (PMID 34183729, 2021).
leiomyoma (1 paper, 2007). A well-circumscribed benign smooth muscle neoplasm characterized by the presence of spindle cells with cigar-shaped nuclei, interlacing fascicles, and a whorled pattern. "They included several genes such as NR2F1, PNN, Smad4, Smad5, STAT5B, JUN, TGIF2, and ATF1 that were over-expressed while RUNX3, STAT1, STAT6, EGR3, GAS7, Smad1, and EDF1 were underexpressed in leiomyomas as compared to keloid/incisional scars." (PMID 17718906, 2007).
leukemia (1 paper, 2018). A malignant (clonal) hematologic disorder, involving hematopoietic stem cells and characterized by the presence of primitive or atypical myeloid or lymphoid cells in the bone marrow and the blood. "High expression of SMAD5 has been found to be associated with the proliferation and differentiation of osteoblasts in regulating leukemia." (PMID 30285885, 2018).
liver fibrosis (1 paper, 2022). "Since the genes of Smad4, Jun, Ctnnb1, and Smad5 have been reported to be associated with liver fibrosis, and the Notch2 gene was considered to be related to Wnt and TGF-β signaling pathways, these five candidate target genes were selected for research." (PMID 35883205, 2022).
lymphoid neoplasm (1 paper, 2022). A neoplasm composed of a lymphocytic cell population which is usually malignant (clonal) by molecular genetic and/or immunophenotypic analysis. "In DLBCL patients, the BMP signaling pathway activates SMAD5, which plays a tumor-suppressive role in lymphoid neoplasms." (PMID 36466549, 2022).
mesenchymal tumours (1 paper, 2017). "Part of this variability may be explained by retained expression of SMAD5, which is the key intracellular mediator between the BMP and Notch pathways, in the intestinal epithelium in mesenchymal tumours." (PMID 28299802, 2017).
metastasis (1 paper, 2019). The spread or migration of cancer cells from one part of the body (where they first appeared) to another. "Chi-square test analysis revealed that upregulated expression of SMAD5 and SMAD5-AS1 and downregulated expression of miR-195 were correlated to larger tumor size, lymph node metastasis and advanced tumor stage." (PMID 31921616, 2019).
metastatic prostate carcinoma (1 paper, 2012). A carcinoma that arises from the prostate gland and has spread to other anatomic sites. "We have presented evidence that integration of two different signaling pathways (CD44 and αvβ3) facilitate osteoclastogenesis and bone loss via a RUNX2/Smad5/RANKL axis in metastatic prostate cancer cells." (PMID 22966907, 2012).
pulpitis (1 paper, 2023). Inflammation of the dental pulp. "SMAD5 regulates miR-135b in terms of odontoblast-like differentiation in HDPCs,28 indicating that SMAD5 may be correlated with pulpitis." (PMID 37272598, 2023).
serous ovarian cancer (1 paper, 2023). "A study with serous ovarian cancer cells reported that activation of the BMP/SMAD‐5 signalling pathway resulted in enhanced proliferative activity." (PMID 37688374, 2023).
Ureteral obstruction (1 paper, 2024). Obstruction of the flow of urine through the ureter. "miR-186-5p in MSC-EVs binds to the 3'-UTR of Smad5 and thus down-regulates Smad5 expression, attenuating renal injury/fibrosis in a unilateral ureteral obstruction model by inhibiting ECM protein aggregation and epithelial-mesenchymal transition." (PMID 39698413, 2024).
tumor (44 papers, 2010 to 2026). "Rho-associated protein kinase 1 (ROCK1) directly phosphorylates Smad5, enhancing vasculogenic mimicry and stemness in tumor cells." (PMID 39578779, 2024). "In renal cell carcinoma, BMP-6 can induce IL-10-dependent M2 polarization of tumor-associated macrophages, a process that relies on Smad5 and STAT3." (PMID 39578779, 2024). "Smad5 is a member of Smad family that are implicated in transforming growth factor-β (TGF-β) signaling in tumor development and metastasis." (PMID 33911345, 2021). "In conclusion, we discovered miR-145-5p′s tumour suppressive function in GC, acting by blocking cell cycle entry and preventing GC cell growth by targeting SMAD5." (PMID 40852585, 2025). "For example, lncRNA SNHG16 in breast cancer-derived EVs expands the population of CD73 + γδ T cells through the TGF-β1/Smad5 pathway, thereby boosting the production of pro-tumor metabolite and adenosine to promote tumor growth." (PMID 40908470, 2025). "Overexpression of SMAD3, SMAD4, and SMAD5 suggests excessive activation of the TGFβ pathway, potentially promoting tumor growth and development." (PMID 39337574, 2024). "Their study revealed that miR-145 overexpression contributes to tumor progression by downregulating the mothers against decapentaplegic homolog 5 (SMAD5), a gene involved in suppressing tumor growth." (PMID 39408872, 2024). "As previously published, BMP signaling, particularly through SMAD5, can promote cancer cell proliferation and tumor growth." (PMID 35805024, 2022). "This miRNA was found to inhibit the malignant behaviors including proliferation, invasion and migration of NPC and the tumor growth in vivo, during which the down-regulation of Smad5 and Wnt/β-catenin signaling was possibly involved." (PMID 33911345, 2021). "Previous studies reported that SMAD5 was a tumor suppressor, which served as a crucial intracellular inhibitor of TGF-β signaling pathway." (PMID 32936232, 2020). "The expression of SMAD5 in hepatocellular was upregulated in carcinoma tissues compared with adjacent non-tumor tissues." (PMID 31168355, 2019). "ALDH1 activity was significantly reduced in MDA-MB 231 cells treated with siRNA-SMAD5, corroborating the findings that SMAD5 expression is required to promote tumor stemness and chemoresistance." (PMID 29207686, 2017). "Taken together, these findings demonstrate that SMAD5 expression is required to induce chemoresistance through maintenance of tumor stemness in TNBC cells." (PMID 29207686, 2017). "In agreement with our previous results, Aurora-A-induced drug resistance was linked to phosphorylation of SMAD5, a key transcription factor downstream of TGF-b/BMP signaling involved in tumor progression." (PMID 29207686, 2017). "The knockout of SMAD1 and SMAD5 in somatic cells of male and female gonads promotes metastatic granulosa cell tumorigenesis in mice, which implicated SMAD1 and SMAD5 as critical tumor suppressors." (PMID 27661009, 2016). "As a key mediator of BMP/Smad pathway, Smad5 can act as a target of microRNA to suppress the endothelial development and thereby the angiogenesis, a must for tumor progression and tumor metastases." (PMID 27438143, 2016). "Another potential mediator of the tumor-suppressive ability of miR-135b is SMAD5, which has been recently identified as one of the target of miR-135b activated by the transcription factor PAX6." (PMID 26437223, 2015). "SMAD5 has been characterized alternatively as a tumor suppressor or growth promoter, depending on cell context, so its specific function in response to gefitinib will require further study to fully understand." (PMID 20579378, 2010). "Overexpression of SMAD3, SMAD4, and SMAD5 indicates excessive stimulation of the TGFβ pathway, which may promote tumor proliferation and development." (PMID 39337574, 2024). "SMAD5 was found to be a tumor suppressor candidate and CDH1 is a tumor suppressor, too." (PMID 36835463, 2023).
tumor (continued). "We speculated that the RhoC/ROCK1 pathway activated by TEM8 could activate SMAD5, which was involved in the stemness of tumor cells and tumor angiogenesis." (PMID 34285210, 2021). "Reduced SMAD1 and SMAD4 expression was seen across all cancer subtypes, but SMAD5 was differentially expressed: it was downregulated in canonical tumours (n = 149), but was retained and modestly upregulated in poor‐prognosis, mesenchymal tumours (n = 78)." (PMID 28299802, 2017). "Our data confirmed that tumor-activated TGFβ/Smad1/5 phosphorylation was regulated by synergistic activation of notch and TGFβ pathway by showing that TGFβ and Jag1 were capable of inducing Smad5 phosphorylation as well as Hes1 up-regulation." (PMID 25623554, 2015). "Knocking out PGC specification inducers (ACVR1, SMAD5, PRDM1, or SOX17) or fate-maintaining genes (NANOG or DDX4) suppressed both SPLC and tumor initiation." (PMID 42291258, 2026). "According to recent research, Id3 is correlated with tumor grades in human astrocytes and is downstream of the EGFR/AKT/Smad5 pathway." (PMID 35599595, 2022). "When the same analyses were done using PEA Oncology II profiling data, 10 proteins correlated to tumor stage (P < 0.05), for example, CD160, TNFRSF4/OX40L, XPNPEP2, SPARC, MAD homolog 5/SMAD5, CPE, hK8/KLK8, WIF‐1, TCL1A, and MIC‐A/B." (PMID 33768639, 2021). "The in vivo xenograft experiments also showed that SMAD5 knockdown suppressed TEM8-enhanced tumor growth, and the enrichment of BTICs, as well as the increase in tumor VM density." (PMID 34285210, 2021). "To conclude, miR-384 targets Smad5 and inactivates the Wnt/β-catenin pathway, which exerts a suppressing role in NPC cell behaviors as well as tumor growth in vivo." (PMID 33911345, 2021). "The top TFs found to negatively regulate the expression of cell cycle genes (SMAD5, IKZF1, USF1, USF2) have been previously shown to have a role as transcriptional repressors and as inhibitors of cellular proliferation in tumor cell lines." (PMID 28899340, 2017). "RHOA, SMAD2, SMAD4, SMAD5, SMAD6, BMPR1A, SMAD7 and MYC-, which thereby emerge as candidate genes to play an important role in CRC tumor metastasis." (PMID 27662660, 2016). "The aberrant Aurora-A kinase activity induced phosphorylation and nuclear translocation of SMAD5, indicating a novel interplay between Aurora-A and SMAD5 signaling pathways in the development of EMT, stemness and ultimately tumor progression." (PMID 25051360, 2014). "Gene expression profiling revealed human genes involved in TGF-β signalling differentially expressed between both tumour groups, that is, TGFBR2 and SMAD5 were lower expressed whereas the inhibitory SMAD7 was higher expressed with VEGFA165." (PMID 22045186, 2011). "TGFBR2, SMAD3, SMAD5, SOS1 and SOS2 were found to be lower expressed in VEGFA165 tumours compared with control tumours." (PMID 22045186, 2011). "Notable, genes involved in TGF-β signalling (SOS1, SOS2, SMAD5, LTBP3, TGFBR2, IRF7 and CREBZF) were found to be significantly (P<0.01) downregulated in the VEGFA165 tumours." (PMID 22045186, 2011). "The importance of ALK1 and SMAD1/5 for endothelial/vascular function is demonstrated by the observations, that genetic elimination of either ALK1 or SMAD5 is embryonic lethal due to cardiovascular defects and that ablation of ALK1 decreased tumor angiogenesis in adult mice." (PMID 22761782, 2012). "Conversely, pharmacologic targeting of Aurora-A restores chemosensitivity through inhibition of SMAD5 transcriptional activity leading to restoration of a more differentiated luminal CD44-/CD24+/PROCR- phenotype with low ALDH1 activity and impairment of tumor stemness." (PMID 29207686, 2017). "Moreover, the aberrant Aurora-A kinase activity induced phosphorylation and nuclear translocation of SMAD5, suggesting a novel interplay between Aurora-A and SMAD5 signaling pathways which may be important in the development of EMT, stemness and ultimately tumor progression." (PMID 23455493, 2012).
cancer (31 papers, 2012 to 2025). A tumor composed of atypical neoplastic, often pleomorphic cells that invade other tissues. "Significantly, molecular targeting of SMAD5 expression was linked to inhibition of a CD44+/CD24-/PROCR+ cancer stem cell-like phenotype and low ALDH1 activity." (PMID 29207686, 2017). "Similarly, SMAD5 has been widely implicated in apoptosis, cancer, and the development of the nervous system." (PMID 34281203, 2021). "Similar to human TPCS, the expression level of the BMP downstream TF Smad5 is increased in cancer TPCS compared to non‐malignant BsP." (PMID 38582099, 2024). "TGF-β secreted by cancer cells upregulates BCAT1 activity by activating SMAD5 in CAFs, thereby increasing the secretion of BCKAs, which are supplied to cancer cells for BCAA synthesis." (PMID 37033960, 2023). "BCAT1 overexpression results in increased BCAA catabolism in cancer and is upregulated by several molecules (e.g., hypoxia-inducible factor 1, SMAD5, cMyc, Musashi2) although some cancers favor the reverse reaction." (PMID 37755304, 2023). "Next, we reorganized the mRNAs that significantly correlated with cancer progression and linked their upstream miRNA and lncRNA, such as ISPD-AS1-has-miR-148a-5p-SMAD5, and PARD6G-AS1-has-miR-493-5p-PFN2." (PMID 33859940, 2021). "SMAD5 is the major component of the SMAD1/5/9 complex that is often activated by BMP in several cancer types." (PMID 33426064, 2020). "Other studies found that miR-145 regulated TGF-β1- (transforming growth factor-β1-) mediated EMT progress to enhance the invasiveness of cancer cells by targeting SMAD5." (PMID 31885571, 2019). "Alternatively, increased expression of CEBPG and SMAD5, transcription factors with known roles in cancer cell metastasis via Hippo and BMP pathways respectively, suggests roles for additional signaling events in modulating the invasive behavior of SW-13 cells." (PMID 29884238, 2018). "As suggested, miR-93 and Smad5 closely correlated with cancer metastasis." (PMID 27438143, 2016). "Validated miR-155 target genes are present in multiple pathways associated with cancer and cancer progression, including EMT (SMAD5), proliferation (SOCS1, INPP5D, and CSF1R), block of differentiation (SPI1, CEBPB), and apoptosis (CASP3, FADD, APAF1, and FOXO3A)." (PMID 27128908, 2016). "In addition, we compared SMAD5 expression between 347 cancer and 50 adjacent normal tissues, and found significantly greater expression in CRC samples (P = 6.56 × 10−7, CRC tissue: 1323 ± 423 RPKM (reads per kilobases per million reads), peritumor tissue: 1020 ± 294 RPKM)." (PMID 27177089, 2016). "There was a greater difference in the expression of SMAD2, SMAD3, SMAD4, SMAD5, and SMAD9 between cancer and normal samples." (PMID 38514720, 2024). "The results show that, except for SMAD5 and SMARCA5, the remaining four genes have significant prognostic ability in multiple cancers, while SMAD5 and SMARCA5 exhibit marginal statistical significance in survival analysis for some cancer datasets." (PMID 39186807, 2024). "For the remaining 17 genes, DNMT3B, RARB, SMAD5, SMARCA5, SMARCC1 and TGFBRAP1 were predicted only by our method, but various evidence suggests that they have a driving role in cancer development." (PMID 39186807, 2024). "A report on the oncogenic role of lncRNA SNHG16 (small nucleolar RNA host 16) in various cancer types and its involvement in many signaling pathways, such as TGF-β1/SMAD5, mTOR, NF-kB, Wnt, RAS/RAF/MEK/ERK, and PI3K/AKT, was published." (PMID 36362406, 2022). "TGF-β1/SMAD5, mTOR, NF-κB, RAS/RAF/MEK/ERK, PI3K/AKT, and Wnt/β-catenin pathways are among cancer-related pathways being affected by this lncRNA." (PMID 34671603, 2021). "Stage 4 is characterized by high progression of cancer, and therefore, only SMAD3, SMAD5, and SMAD9 showed prognostic significance in this stage." (PMID 34138687, 2021).
cancer (continued). "Because treatment with PTX induces G2/M cell cycle arrest in chemosensitive cancer cells, MDA-MB 231 cells were treated with PTX and/or siRNAs targeting SMAD5 (Scramble siRNAs were used as control) and cell cycle profile was analyzed by FACS assay." (PMID 29207686, 2017). "Moreover, ZEB2 correlates with SMAD1 in 28 cancer types, SMAD2 in 27 cancer types, SMAD3 in 22 cancer types, SMAD5 in 28 cancer types, CTBP1 in 14 cancer types, and CTBP2 in 22 cancer types." (PMID 35723302, 2022). "Some studies showed that the induction of miR-135a expression in different types of cancers could suppress cell proliferation through target genes (c-MYC, STAT6, SMAD5, and BMPR2)." (PMID 34377051, 2021). "Moreover, treatment with siRNA-SMAD5 induced a luminal CD44-/CD24+ phenotype in MDA-MB 231 cells, indicating that SMAD5 expression is required to maintain a CD44+/CD24- cancer stem cell-like phenotype." (PMID 29207686, 2017).
respiratory diseases (1 paper, 2024). "In summary, Smad5 signaling pathway has an important role in the pathogenesis of respiratory diseases, and inhibition or over-activation of BMP signaling will lead to adverse effects." (PMID 39578779, 2024). "Numerous studies suggest that Smad5 may play a unique and important role in the pathogenesis of respiratory system diseases." (PMID 39578779, 2024). "Given that Smad5 can move intracellularly in response to changes in physicochemical properties, its cellular localization may play a crucial role in the development of respiratory diseases." (PMID 39578779, 2024).
SMAD5 also shares sentences with these, for which no sentence is quoted: atherosclerosis (2 papers); Colon Cancer (2); pulmonary arterial hypertension (2); adenocarcinoma (1); Alzheimer disease (1); amyotrophic lateral sclerosis (1); astrocytic tumor (1); brain tumor (1); cervical cancer (1); cervical tumors (1); Chagas disease (1); Chronic colitis (1); chronic obstructive pulmonary disease (1); congenital heart disease (1); dialysis (1); familial pulmonary arterial hypertension (1); female infertility (1); injury (1); lung adenocarcinoma (1); macular degeneration (1); melanoma (1); multiple myeloma (1); myopia (1); osteonecrosis (1); Peritoneal Fibrosis (1); simian immunodeficiency virus infection (1); syndactyly (1); tongue cancer (1); type 2 diabetes mellitus (1).